CD38 (CD38 molecule)
Diseases named in the same sentence as CD38 in open-access papers (continued):
Sharing a sentence is not in itself a finding about the gene and the disease.
Obesity (continued). "Experiments conducted using CD38 knockout mice supported these findings, leading to the conclusion that CD38 can be considered a relevant molecular target to combat obesity-induced insulin resistance." (PMID 37761000, 2023). "A follow-up study confirmed that CD38 knockout mice are protected from diet-induced obesity and demonstrated high NAD+ levels in their WAT and BAT on a high-fat, high-sucrose diet." (PMID 37761000, 2023). "CD38 inhibition in a mouse model of HFD-induced obesity treated with the flavonoid apigenin showed a reduction in lipid accumulation in the liver through increased lipid oxidation." (PMID 36794157, 2023). "Numerous studies have shown that CD38 is involved in the pathological processes of many diseases including aging, obesity, cardiovascular diseases, cancer, and inflammation." (PMID 37958991, 2023). "Inhibitors of CD38, such as the flavonoid apigenin from foods such as parsley, have shown beneficial effects in tackling obesity in animal models." (PMID 35348641, 2022). "The protein CD38 participates in the pathogenesis and regulation of metabolism in a variety of diseases, including obesity, diabetes, heart disease, asthma, and inflammation." (PMID 36439479, 2022). "Our previous studies showed that CD38-/- mice were resistant to high-fat diet (HFD)-induced obesity." (PMID 34803499, 2021). "It has been reported that overexpression of CD38 leads to acetylation of proteins which results in the protein degeneration in obesity." (PMID 34679777, 2021). "CD38 inhibition protects from high-fat diet-induced obesity via NAD+-dependent SIRT1/PGC-1α signaling and attenuates renal vasoconstriction caused by angiotensin II, ET-1, and norepinephrine." (PMID 34368195, 2021). "Several studies reported that CD38 knockout mice are protected against high-fat diet-induced obesity, hyperglycemia, and hyperinsulinemia as a consequence of enhanced energy expenditure." (PMID 34835990, 2021). "Previous studies have shown that CD38-knockout mice exhibit higher NAD+ levels and reduced metabolic syndrome in obesity, and CD38 inhibitors elevate cellular NAD+ levels and improve various aspects of both glucose and lipid homeostasis." (PMID 33925372, 2021). "As literature suggested a role for CD38 in the prevention of diet-induced obesity, the drug metabolism and pharmacokinetic characterization of the quinoline series was originally performed in obese WT mice." (PMID 33092650, 2020). "A high-fat caloric diet induces obesity through the protein CD38, which is a regulator of body weight and an NAD+ consumer." (PMID 33414897, 2020). "According to recent studies, CD38 KO mice are resistant to a high-fat diet or a high-fat, high-sucrose diet, both of which usually induce obesity in WT mice." (PMID 33326496, 2020). "Numerous studies have linked CD38, which modulates cellular NAD homeostasis, to the pathogeneses of multiple conditions, including aging, obesity, diabetes, asthma, and inflammation." (PMID 32363189, 2020). "In this study, to explore the roles of CD38 in adipogenesis and lipogenesis in vivo and in vitro, obesity models were generated with male CD38−/− and WT mice fed with HFD." (PMID 28816006, 2018). "It has been recently reported that CD38 was highly expressed in adipose tissues from obese people and CD38‐deficient mice were resistant to high‐fat diet (HFD)‐induced obesity." (PMID 28816006, 2018). "Mice bearing a genetic deletion of CD38 were protected from diet-induced obesity, hyperglycemia and hyperinsulinemia." (PMID 26287487, 2015). "Low Igfbp1 levels are considered to be markers of metabolic syndrome and the Igfbp1 transgenic mice are protected from diet-induced obesity, a trait shared by the CD38-null mice." (PMID 21937766, 2011). "Along these lines, drugs targeting CD38 inhibition or NAD supplementation are only just recently being considered in obesity research." (PMID 18752667, 2008).
Obesity (continued). "Given that increased levels of nicotinamide adenine dinucleotide (NAD) via deletion of CD38 have been shown to prevent high fat diet induced obesity in mice in a SIRT-1 dependent fashion we explored the possibility of directly applying NAD to zebrafish." (PMID 18752667, 2008). "The activity of CD38 increases with ageing and diet-induced obesity, leading to NAD+ decline." (PMID 39199240, 2024). "However, there are only a handful of papers about the involvement of CD38 in metabolic disturbances in obesity." (PMID 37761000, 2023). "CD38 inhibition by flavonoids including apigenin and quercetin also improves glucose homeostasis and promotes fatty acid oxidation in the liver of mice with high-fat-diet-induced obesity, possibly through the activation of sirtuins such as Sirt1 and Sirt3." (PMID 36831262, 2023). "Furthermore, aging and HFD-induced obesity increase CD38 expression in macrophages and the vascular endothelium." (PMID 36986224, 2023). "We previously observed that deletion of CD38 significantly inhibited HFD-induced obesity in mice." (PMID 34803499, 2021). "In line, low expression of CD38 protected against obesity when fed a high-fat diet in animals." (PMID 33414897, 2020). "To determine whether CD38 expression might be altered in obesity, we then assayed CD38 expression in white adipose tissue from WT mice fed with HFD." (PMID 28816006, 2018). "The results showed that CD38−/− male mice were significantly resistant to HFD‐induced obesity." (PMID 28816006, 2018). "It has been reported that deletion of CD38 gene protected mice from HFD‐induced obesity." (PMID 28816006, 2018). "Interestingly, CD38-KO mice are resistant to high-fat diet-induced obesity, in part through the activation of the SIRT1-PGC1α axis." (PMID 21937766, 2011). "Thus, suppression of CD38 may be beneficial for protection against aging, a shortened health span, age-related diseases, high-fat-diet-induced obesity and metabolic dysfunction." (PMID 36831262, 2023). "Thus, the role of CD38 as a regulator of obesity and energy expenditure may also be related to thermogenesis and mediated by a NAD+-SIRT-dependent mechanism." (PMID 36794157, 2023). "CD38 is involved in cellular metabolism through regulation of the NAD pool and in the pathogenesis of many conditions, including diabetes, obesity, heart disease, asthma, aging and inflammation." (PMID 38472945, 2024). "Our findings highlight the significant contribution of the hypothalamic astrocytic NAD+ salvage pathway, along with its downstream CD38, to HFD-induced obesity." (PMID 38453901, 2024). "To further interrogate how functional differentiation pathways are affected by obesity and bariatric surgery, we next assessed CXCR5+CD11c-IgD-CD27- DN1 and CD11c+CXCR5-IgD-CD27- DN2 B cell subset as well as CD27+CD38++ plasmablast frequencies." (PMID 37463992, 2023). "In these models, elevated cellular levels of NAD+ are beneficial, and CD38 knockout increases the NAD+ levels and protects against obesity." (PMID 35348641, 2022). "On the contrary, the inhibition of CD38 by boosting NAD+ levels, can improve glucose and lipid metabolism, by protecting against age- and diet-induced diabetes and obesity." (PMID 35087020, 2022). "CD38 KO mice have globally elevated tissue NAD+ levels and, relative to controls, are protected against diet-induced obesity and metabolic syndrome." (PMID 26287487, 2015). "Inhibition of CD38 leads to higher NAD+ levels and protection against obesity and MetS in mice." (PMID 38629096, 2024). "Therefore, CD38 expression increases with age and HFD-induced obesity in major organs such as the liver, skeletal muscle, and lungs, decreasing NAD+ levels." (PMID 36986224, 2023). "Emerging reports indicate that mammalian cells have key NAD+ ase in the form of CD38 and that the manipulation of NAD+ metabolism may represent a plausible strategy to ameliorate obesity, metabolic syndrome and type 2 diabetes." (PMID 34679777, 2021).
Obesity (continued). "Similar to Emr1, higher levels of Entpd1, Cd38, and Nt5e were found in BAT of ob/ob mice, while no obesity-associated changes in Ucp1 expression were detected." (PMID 33025427, 2020). "Therefore, CD38 represents an important regulator of SIRT1 activity and SIRT1 functions, including maintenance of cellular bioenergetics, obesity and senescence, mainly because it modulates the availability of NAD+ to the SIRT1 enzyme." (PMID 32423100, 2020). "CD38 knockout mice show decreased cADPR and increased NAD+ concentrations, which may protect from inflammation, apoptosis, oxidative stress, and high-fat diet induced obesity." (PMID 34368195, 2021).
influenza (44 papers, 2010 to 2026). An acute viral infection of the respiratory tract, occurring in isolated cases, in epidemics, or in pandemics; it is caused by serologically different strains of viruses (influenzaviruses) designated A, B, and C, has a 3-day incubation period, and usually lasts for 3 to 10 days. "Immune stability was significantly lower in immunotypes that contained aging‐associated immune subsets and correlated with a circulating CD38 + CD4+ T follicular helper cell increase 7 days after influenza vaccination." (PMID 36081314, 2022). "In previous studies, ICOS and CD38 upregulation was associated with the presence of a cTfh cell phenotype on bulk CD4 T cells after influenza vaccination." (PMID 34795301, 2021). "We utilized surface expression of CD38 on newly activated CD4 memory T cells as a strategy to identify type 1 diabetes associated autoreactive T cells activated by influenza vaccination in healthy subjects." (PMID 30619245, 2018). "Mild influenza illness was associated with transient expression of activation markers CD38 and HLADR on a small percentage and number of CD8 T-cells." (PMID 22363665, 2012). "In addition, we showed that immune stability was associated with immune immunotypes and circulating CD38+ CD4+ T follicular cell increase 7 days after influenza vaccination." (PMID 36081314, 2022). "In contrast to mild influenza patients, T cell activation (expression of CD38 and HLA-DR) in severe influenza patients was delayed and/or exaggerated and associated with accumulation of partially differentiated cells suggesting disturbed migration of the effector cells to the site of infection." (PMID 35392095, 2022). "Furthermore, we show that longitudinal intra‐individual variation, which reflects immune stability, was associated with circulating CD38+ CD4+ T follicular cell kinetics 7 days after influenza vaccination." (PMID 36081314, 2022). "Expression of IL-18Rα increased concurrently with additional activation markers such as CD38, HLA-DR or PD-1 in influenza-specific CD8 T cells." (PMID 41285788, 2025). "Contrary to influenza-specific cells, the expression of HLA-DR and CD38 in memory cit-TNC CD4+T cells was confined to only a few individuals, while being commonly expressed in the former cell population." (PMID 39557489, 2024). "Increased frequencies of ICOS+ cTfh‐1 and ICOS+CD38+ cTfh cells have also been correlated with higher immunoglobulin G antibody levels in separate studies of influenza and pneumococcal vaccination." (PMID 36825370, 2023). "CD8+ T cells that express CD38 and HLA-DR have been described in severe influenza infection, HIV infection, and MIS-C." (PMID 37751296, 2023). "This is in line with our observation where immunotypes 2 and 7 with low immune stability, higher regulatory pressure and potentially inflammaging driven remodulation showed lower CD38+ CD4+ T follicular cell increase 7 days after influenza vaccination." (PMID 36081314, 2022). "The recruitment of cycling and activated (CD38+HLA-DR+) CD8+ T cells subset is delayed in severe influenza patients." (PMID 36064355, 2022). "Our results showed that immune stability correlated with a circulating CD38+ CD4+ T follicular cell increase 7 days after influenza vaccination." (PMID 36081314, 2022). "Co-expression of Human Leukocyte Antigen DR (HLA-DR) and CD38 associated with activation of CD8+ T cells was reported to accumulate over a prolonged period from the lymphopenia patients who died from Ebola and influenza infection." (PMID 34567001, 2021). "Previous studies analyzing bulk cTfh cells after influenza vaccination identified a peak of activation on day 7 characterized by CD38, ICOS, and CXCR3 expression." (PMID 34795301, 2021). "Patients with seroconversion to all three influenza vaccine strains were found to have higher CD38+CD4+ T cells pre-vaccination." (PMID 32012159, 2020).
influenza (continued). "This expansion of ICOS+CD38+CXCR5+PD-1+ cTfh cells correlated positively with the increase in influenza-specific antibodies 7 and 42 d after vaccination." (PMID 31175140, 2019). "We postulated that autoreactive islet antigen specific T cells that can cross react to influenza antigen will also up-regulate CD38 upon influenza vaccination, allowing a means of effectively identifying such cells." (PMID 30619245, 2018). "Specifically, resting memory influenza specific CD4+ T cells are CD38-, but become CD38 bright in the periphery starting 7–14 days after influenza vaccination or infection." (PMID 30619245, 2018). "Cell surface expression of CD38 in influenza specific cells remains upregulated for more than a month following vaccination but, declines to basal levels in about 2 months after antigen clearance." (PMID 30619245, 2018). "Comparing CD38 expression in influenza specific CD4+/CD45RO+ memory T cells in pre and 14 days post influenza vaccination samples, we observed that CD38 expression was only present in the post vaccination samples." (PMID 30619245, 2018). "There were insufficient data for statistical analysis of influenza-specific CD38 expression between groups." (PMID 28520789, 2017). "As expected, CD38 levels were low for the influenza-specific cells before vaccination and displayed a significant increase after vaccination for all epitopes except PeHA-322, which was absent in the vaccine strains." (PMID 27571776, 2016). "In severe influenza CD8 activation peaked more than 9 days post-onset, and/or was excessive (30–90% HLADR+CD38+) in association with accumulation of CD27+CD28− cells and maintenance of CD8 counts." (PMID 22363665, 2012). "HLA-DR and CD38 co-staining was used to estimate the percentage responding to influenza since the vast majority of CD8 T cells co-expressing these markers are specific for the infecting agent." (PMID 22363665, 2012). "CD8 activation peaked 6–8 days after mild influenza onset, when 13% (6–22%) were HLADR+CD38+, and was accompanied by a significant loss of resting/CD27+CD28+ cells without accumulation of CD27+CD28− or CD27−CD28− cells." (PMID 22363665, 2012). "Protection against influenza infection has been associated with various factors, including the presence of influenza-specific serum antibodies, polyfunctional B and T cells, particularly IFNγ-producing CD4+ T cells, memory CD8+ T cells, and CD38+ plasmacytoid dendritic cells (pDCs)." (PMID 40766325, 2025). "Thus far, post‐vaccination changes in numbers of circulating follicular (CXCR5+) CD4+ T cells and plasmablasts (CD19 + CD27 + CD38+) at day 7 were described as some of the best correlates of antibody responses to influenza vaccination." (PMID 38146131, 2024). "Another study reported that age-related inefficiency of a trivalent influenza vaccine response was associated with lower frequencies of transitional (IgD+CD27+/-CD38+/-), class-switched memory (SwM), and double-negative (DN) B cells." (PMID 39613759, 2024). "VLRB MM3 binds CD38 in a manner that correlates with enzymatic activity and specifically recognizes CD38 on human plasma cells from the tonsil, spleen, and bone marrow, as well as peripheral blood plasmablasts following influenza vaccination." (PMID 39575239, 2024). "after the first dose of BNT162b2 vaccination (and a slight increase upon second dose) among the cTfh cells (PD‐1+CXCR5+) that expressed ICOS+CD38+, wherein these activated cells have been correlated with antibody responses and overlapping clonality after successive influenza vaccinations." (PMID 36825370, 2023). "In influenza patients, the majority of CD38 + HLA-DR + CD8 cells expressed PD-1: after recovery, all activated CD8 cells had intermediate levels of PD-1 expression, while cells with both intermediate and high expression of PD-1 were present within fatally ill patients." (PMID 36752852, 2023). "In prior studies, antigen-specific ICOS+CD38+ cTfh expressed CXCR3 following influenza vaccination." (PMID 34874183, 2022).